HBB (hemoglobin subunit beta)
Description:
Involved in oxygen transport from the lung to the various peripheral tissues. LVV-hemorphin-7 potentiates the activity of bradykinin, causing a decrease in blood pressure. [Spinorphin]: Functions as an endogenous inhibitor of enkephalin-degrading enzymes such as DPP3, and as a selective antagonist of the P2RX3 receptor which is involved in pain signaling, these properties implicate it as a regulator of pain and inflammation.
Synonyms: CD113t-C; beta-globin; ECYT6
Tractability: Small molecule: an approved drug acts on it; a structure with a bound ligand is known; a high-quality ligand is known; it has a high-quality binding pocket; it belongs to a druggable protein family. Antibody: its Gene Ontology location is reachable by antibodies, with high confidence. PROTAC: a small molecule that binds it is known. Other modalities: an approved drug acts on it.
Target class: Secreted protein
Gene: Protein-coding gene on chromosome 11 (5,225,464 to 5,229,395, reverse strand). Ensembl gene ENSG00000244734.
Pathways (Reactome):
Autophagy: Chaperone Mediated Autophagy; Late endosomal microautophagy
Cellular responses to stimuli: Cytoprotection by HMOX1; Heme signaling
Transport of small molecules: Erythrocytes take up carbon dioxide and release oxygen; Erythrocytes take up oxygen and release carbon dioxide
Disease: Heme assimilation
Hemostasis: Factors involved in megakaryocyte development and platelet production
Immune System: Neutrophil degranulation
Vesicle-mediated transport: Scavenging of heme from plasma
Gene Ontology:
Molecular function: haptoglobin binding; hemoglobin binding; oxygen binding; peroxidase activity; protein binding; heme binding; hemoglobin alpha binding; oxygen carrier activity
Biological process: hydrogen peroxide catabolic process; inflammatory response; nitric oxide transport; oxygen transport; platelet aggregation; renal absorption; response to hydrogen peroxide; carbon dioxide transport; erythrocyte development; positive regulation of nitric oxide biosynthetic process; cellular oxidant detoxification
Cellular component: blood microparticle; extracellular exosome; extracellular region; haptoglobin-hemoglobin complex; hemoglobin complex; cytosol; endocytic vesicle lumen; ficolin-1-rich granule lumen; tertiary granule lumen
Genetic constraint (gnomAD): Loss-of-function variants: 19 observed, 10.56 expected, observed/expected ratio (o/e) 1.8, 90% interval 1.19 to 1.96. The synonymous counts are far from expectation, so gnomAD's model fits this gene poorly and the ratio says little. Missense variants: 153 observed, 181.77 expected, observed/expected ratio (o/e) 0.84, 90% interval 0.74 to 0.96. Synonymous variants: 98 observed, 75.58 expected, observed/expected ratio (o/e) 1.3, 90% interval 1.1 to 1.53.
Gene-disease validity (ClinGen):
ClinGen rates the evidence that HBB causes each of these diseases.
beta-thalassemia HBB/LCRB (autosomal recessive): Definitive. Abnormal clinical manifestations of beta thalassemia that are as a result of the underlying genotype.
dominant beta-thalassemia (autosomal dominant): Definitive.
erythrocytosis, familial, 6 (autosomal dominant): Definitive.
hemoglobin M disease (autosomal dominant): Definitive.
unstable hemoglobin disease (autosomal dominant): Definitive.
Homologues: Orthologues: chimpanzee HBB (100% identical), zebrafish hbaa1 (41% identical), zebrafish si:ch211-5k11.8 (41% identical), zebrafish hbaa2 (40% identical), zebrafish hbae3 (39% identical), zebrafish hbae5 (39% identical), zebrafish hbae1.1 (37% identical), zebrafish hbae1.2 (37% identical), zebrafish hbae1.3 (37% identical), Drosophila melanogaster glob1 (21% identical), Caenorhabditis elegans glb-34 (16% identical), Caenorhabditis elegans glb-14 (13% identical). Paralogues in human: HBD (93% identical), HBE1 (76% identical), HBG2 (73% identical), HBG1 (73% identical), HBA1 (43% identical), HBA2 (43% identical), HBQ1 (38% identical), HBZ (36% identical), HBM (33% identical), CYGB (29% identical), MB (24% identical).
Diseases named in the same sentence as HBB in open-access papers:
HBB is named in the same sentence as 172 diseases in open-access papers, as found by Europe PMC text mining. Sharing a sentence is not in itself a finding about the gene and the disease. The quoted sentences say what the papers report.
sickle cell disease (100 papers, 2011 to 2025). Sickle cell anemias are chronic hemolytic diseases that may induce three types of acute accidents: severe anemia, severe bacterial infections, and ischemic vasoocclusive accidents (VOA) caused by sickle-shaped red blood cells obstructing small blood vessels and capillaries. "Sickle Cell Anemia (SCA) arises from a point mutation in the HBB (hemoglobin subunit beta) gene, which encodes the β-globin subunit of hemoglobin." (PMID 40258044, 2025). "Sickle cell disease (SCD) is a group of inherited blood disorders characterized by mutations in the gene that encodes the hemoglobin subunit β (HBB), resulting in the sickle hemoglobin allele βS (HbS)." (PMID 41373955, 2025). "Sickle cell disease (SCD) is caused by a single A→T (E6V) point mutation in the HBB gene, which leads to the production of sickle hemoglobin (HbS)." (PMID 41373623, 2025). "Sickle cell disease (SCD) is a group of recessive diseases caused by the βS sickling mutation of HBB in homozygosity or in compound heterozygosity with other pathogenic HBB mutations." (PMID 40362693, 2025). "Sickle cell disease is a common genetic disorder caused by a single-point mutation in the HBB gene, leading to HbS synthesis and polymerization under hypoxic conditions." (PMID 40362428, 2025). "Sickle cell disease (SCD) is a genetic blood disorder that is caused by inheriting an abnormal hemoglobin subunit beta (HBB) gene from both parents." (PMID 41166322, 2025). "Sickle cell disease (SCD) is an inherited blood disorder caused by mutations in the hemoglobin subunit beta (HBB) gene and is associated with premature mortality and significant morbidity, including vasoocclusive pain, stroke, and multiorgan damage." (PMID 38547025, 2024). "Sickle cell disease (SCD) is a genetic disorder caused by mutations in the HBB gene, resulting in the abnormal shape of red blood cells." (PMID 39156342, 2024). "Sickle cell disease is an autosomal recessive disorder caused by mutations in the gene HBB, which encodes the β-globin subunit of adult hemoglobin." (PMID 39655010, 2024). "As a positive control, one of the lead variants was rs334 (HBB), a well-established variant at increased frequency in African populations due to balancing selection as it is protective against malaria but causes sickle cell anemia risk allele." (PMID 37425708, 2023). "Sickle cell disease (SCD) is one of the most common severe monogenic disorders in the world caused by a mutation on HBB gene and characterized by hemoglobin polymerization, erythrocyte rigidity, vaso-occlusion, chronic anemia, hemolysis, and vasculopathy." (PMID 36768849, 2023). "For the HBB gene, one amplicon was designed to target variants associated with thalassaemias, sickle cell anaemia (HbS), HbC, HbE, as well as a variety of other haemoglobinopathies, and the average coverage for the HBB amplicon was 2195-fold." (PMID 37495620, 2023). "Sickle cell anemia (SCA) is caused by a single point variation in the β-globin gene (HBB): c.20A> T (p.Glu7Val), in homozygous state." (PMID 36409722, 2022). "Hemoglobin subunit beta (HBB) loci are associated with beta-thalassemia, sickle cell anemia, and heinz body anemias." (PMID 35366954, 2022). "We demonstrated the utility of the double tap method by installing two disease-relevant mutations (an A to T point mutation in the HBB gene that causes sickle cell disease, and a 4-bp insertion in the HEXA gene that causes Tay-Sachs disease)." (PMID 35534455, 2022). "Among one of the most prominent adaptation/disease mutations in this category is that involving hemoglobin beta (HBB) mutations associated with sickle cell anemia (HbS), in global regions prone to malaria." (PMID 35625664, 2022). "Sickle cell anemia (SCA) is caused by abnormal beta-globin alleles that carry a sickle cell mutation within the HBB gene (Glu6Val, βS)." (PMID 35761209, 2022).
sickle cell disease (continued). "In HBB, the Glu-Val missense variant rs334 that causes sickle-cell anemia shows ΠAHz of 194.8, placing it in the top 0.005% of all variants." (PMID 33185667, 2021). "By contrast, carrier frequency of rs334 (p.Glu6Val) in HBB, the most common causative variant of sickle cell anemia, was >30-fold higher in Africans compared to other populations." (PMID 34078906, 2021). "Sickle cell disease (SCD) is an inherited hemoglobinopathy caused by a variant (rs344) in the HBB gene encoding the β-globin subunit of hemoglobin." (PMID 33968971, 2021). "Sickle Cell Disease (SCD) is a severe hereditary form of anemia caused by a single nucleotide mutation altering the sixth codon of the beta globin gene (HBB)." (PMID 32873924, 2021). "Mutation of HBB, the encoding gene of atypical β globin, is associated with sickle cell anemia, and expression of β-globin promotes cell survival in cancer." (PMID 33739370, 2021). "Sickle cell anemia is caused by point mutations in the HBB gene, which codes for β-subunit, where adenine is substituted by thymine (GAG > GTG) at codon 6 of the HBB gene." (PMID 34063111, 2021). "The new Cas9 R691A (HiFi Cas9) was demonstrated to function well in an ex vivo system to repair the p.E6V mutation in the hemoglobin beta (HBB) gene that causes sickle cell anemia." (PMID 31107154, 2019). "Sickle cell anemia (SCA) is a monogenic hematological disorder caused by substitution GAG>GTG at the 6th position of the beta globin gene (HBB) located in chromosome 11." (PMID 31636731, 2019). "The beta-hemoglobinopathies, such as beta-thalassemia and sickle cell disease are caused by beta-globin (HBB) gene mutations which had affected millions of people worldwide." (PMID 31762718, 2019). "Sickle Cell Disease and ß-thalassemia, which are caused by defective or deficient adult ß-globin (HBB) respectively, are the most common serious genetic blood diseases in the world." (PMID 30645582, 2019). "For example, the homozygous single point mutation in the HBB gene, substituting glutamic acid for valine at position 6 leads to sickle cell disease." (PMID 29910743, 2018). "Sickle cell anemia is caused by a single point mutation in the HBB gene at position 6 substituting glutamic acid to valine (HbS)." (PMID 29910743, 2018). "Most of these studies were either focused on HBB gene addition or targeting sickle cell disease mutation." (PMID 30430274, 2018). "Mutations in the HBB gene are responsible for several serious hemoglobinopathies, such as sickle cell anemia and β-thalassemia." (PMID 28379995, 2017). "Mutations in the HBB gene, which is located on chromosome 11 p15.5, are responsible for several serious hemoglobinopathies, such as sickle cell anemia and β-thalassemia." (PMID 28379995, 2017). "The human beta globin gene (HBB) is found mutated to a form that leads to sickle cell anemia, a homozygous recessive disease." (PMID 32309588, 2016). "It is important to point out that researchers have just recently reported that HBB mutations can be repaired in hematopoietic stem cells derived from human sickle cell anemia patients." (PMID 32309588, 2016). "Both sickle cell disease and β-thalassemia are monogenic diseases caused by mutations in the HBB gene." (PMID 26694713, 2015). "New DNA-binding specificities have been engineered in this template, showing that BuD-derived nucleases (BuDNs) induce high levels of gene targeting in a locus of the human haemoglobin β (HBB) gene close to mutations responsible for sickle-cell anaemia." (PMID 25004980, 2014). "We identified known associations at the genes ABO (which affects blood type) and HBB (which causes sickle cell disease), and showed that the latter is heterogeneous across populations." (PMID 23717212, 2013). "It is sometimes claimed that sickle cell anaemia is the simplest of all Mendelian disorders in that it is caused by one specific mutation (Glu7Val) in the β-globin (HBB) gene." (PMID 23820649, 2013).
sickle cell disease (continued). "The HbS allele (Glu6Val in HBB, rs334) leading to sickle-cell anemia, is in LD with rs7120391 (r2 = 0.37)." (PMID 23696099, 2013). "Additionally, sickle cell anemia, caused by the substitution of valine for glutamate in the sixth amino acid of the HBB protein, has been identified through epidemiological studies as an independent risk factor for pneumonia." (PMID 39358504, 2025). "To evaluate whether known variants with ancestral divergence are replicated in the All of Us cohort, we examined the frequency of the rs334 mutation in HBB, known to be associated with sickle cell disease, and the APOL1 G1 and G2 alleles." (PMID 38374434, 2024). "In summary, we observed a predicted LOF variant in the HBB gene, p.Glu7Lys (rs33930165), demonstrating associations with hereditary hemolytic anemias and sickle cell anemia (phecodes = 282 and 282.5, odds ratios [OR] = 5.63 and 6.59, P = 1.26 × 10−13 and 2.8 × 10−11)." (PMID 38037155, 2023). "Alternatively, surface substitutions may lead to the creation of hydrophobic patches which may result in protein aggregation, such as in the case of the haemoglobin S variant, HBB p.(Glu6Val), which causes sickle cell anaemia." (PMID 35869530, 2022). "In fact, late onset ß-thalassemia and sickle cell anemia are other diseases with a similar mechanism of mosaic segmental paternal isodisomy at 11p15 unmasking a pathogenic variant in the HBB gene followed by clonal selection of hematopoetic progenitor cells due to enhanced proliferation." (PMID 36339418, 2022). "Sickle cell disease is caused by a single base substitution at the 6th codon of the HBB gene." (PMID 36250099, 2022). "Mutated HBB can cause sickle cell disease, a common human genetic disease." (PMID 33561926, 2021). "The discovery that ɤ-globin expression from intact HBG alleles complements defective HBB alleles underlying β-thalassemia and sickle cell disease, has provided a promising opening for research directed at relieving ɤ-globin repression mechanisms and, thereby, improve clinical outcomes for patients." (PMID 34713239, 2020). "Moreover, mutations in the HBB gene are responsible for several serious hemoglobinopathies, including sickle cell anemia and Î2-thalassemia." (PMID 33376724, 2020). "Similarly, carrier frequency for variant (c.20A>T: p.Glu7Val) in the HBB gene was observed as 0.0228, which causes thalassemia and sickle cell anemia." (PMID 31557427, 2019). "Sickle cell disease is caused by mutations in the protein-coding HBB gene." (PMID 26589812, 2015). "The non-synonymous variant rs334 in the HBB gene, whose derived allele (HbS) causes sickle-cell anaemia in homozygote individuals and is known to be strongly protective against malaria in heterozygotes, is perhaps the best known case of balancing selection in the genome." (PMID 23717212, 2013). "Multiple lentiviral vectors carrying the HBB gene sequence were developed for gene therapy of β-thalassemia and sickle cell disease." (PMID 41373623, 2025). "For example, the missense causal variants of HBB and G6PD for sickle cell disease and anaemia, respectively, were >1,500× more common in AFR versus NFE, owing to their protection against severe malaria and the fact that 95% of malaria cases occur in Africa51." (PMID 40770095, 2025). "Symptoms of sickle cell disease appear during infancy as γ-globin gene (HBG1 and HBG2) transcription switches to HBB, causing a shift from fetal hemoglobin to adult hemoglobin in red cells." (PMID 39655010, 2024). "Sickle cell disease (SCD) is an inherited blood disorder, due to a single point mutation in the β-globin gene (HBB) leading to multisystemic manifestations and it affects millions of people worldwide." (PMID 38027257, 2023). "A relatively high number of suppressor genes have been identified for HBB and CFTR, which are mutated in sickle cell disease/β-thalassemia and cystic fibrosis patients, respectively." (PMID 37821946, 2023).